KBTBD12 (kelch repeat and BTB domain containing 12)
Synonyms: KLHDC6; FLJ46299
Tractability: Small molecule: it belongs to a druggable protein family.
Gene: Protein-coding gene on chromosome 3 (127,915,207 to 127,989,100, forward strand). Ensembl gene ENSG00000187715.
Gene Ontology:
Molecular function: ubiquitin-like ligase-substrate adaptor activity
Biological process: proteasome-mediated ubiquitin-dependent protein catabolic process
Cellular component: Cul3-RING ubiquitin ligase complex; cytoplasm
Genetic constraint (gnomAD): Loss-of-function variants: 53 observed, 56.96 expected, observed/expected ratio (o/e) 0.93, 90% interval 0.75 to 1.17. The upper end of that interval is the gene's LOEUF score, 1.17, which puts it in group 5 of 6, group 1 being the genes least tolerant of losing a copy. Missense variants: 682 observed, 756.63 expected, observed/expected ratio (o/e) 0.9, 90% interval 0.85 to 0.96. Synonymous variants: 225 observed, 264.17 expected, observed/expected ratio (o/e) 0.85, 90% interval 0.76 to 0.95.
Homologues: Orthologues: chimpanzee KBTBD12 (99% identical), macaque KBTBD12 (98% identical), dog KBTBD12 (94% identical), guinea pig KBTBD12 (92% identical), pig KBTBD12 (92% identical), mouse Kbtbd12 (92% identical), rat Kbtbd12 (91% identical), rabbit KBTBD12 (83% identical), tropical clawed frog kbtbd12 (68% identical), zebrafish kbtbd12 (56% identical). Paralogues in human: KBTBD8 (24% identical), KLHL17 (24% identical), KLHL4 (24% identical), KBTBD2 (24% identical), KLHL24 (24% identical), KLHL20 (24% identical), KBTBD7 (23% identical), KLHL3 (23% identical), KLHL2 (23% identical), KLHL5 (23% identical), KLHL12 (23% identical), KLHL6 (22% identical), and 42 more.
Diseases named in the same sentence as KBTBD12 in open-access papers:
KBTBD12 is named in the same sentence as 5 diseases in open-access papers, as found by Europe PMC text mining. Sharing a sentence is not in itself a finding about the gene and the disease. The quoted sentences say what the papers report.
colorectal adenoma (2 papers, 2022 to 2024). An adenoma that arises from the colon or rectum. "KBTBD12 expression was downregulated in colorectal adenoma compared with hyperplastic polyps." (PMID 35884544, 2022).
lung carcinoma (1 paper, 2022). "The function of ANKRD13B, FBXL8, and KBTBD12 in the carcinogenesis and progression of lung cancer need to be further investigated." (PMID 35884544, 2022).
tumor (1 paper, 2022). "ANKRD13B, ISG15, KBTBD12, KLHL35, and UHRF1 were upregulated in tumor samples; DCUN1D5, HCK, and SOCS3 were downregulated in tumor than in normal samples." (PMID 35884544, 2022).
KBTBD12 also shares sentences with these, for which no sentence is quoted: cancer (2 papers); hyperplastic polyp (1).